REN (renin)
Diseases named in the same sentence as REN in open-access papers (continued):
Sharing a sentence is not in itself a finding about the gene and the disease.
chronic kidney disease (continued). "In the majority of cases, HK is associated with chronic kidney disease (CKD), or with the use of renin–angiotensin–aldosterone system inhibitors (RAASis) and/or mineral corticoid antagonists (MRAs)." (PMID 35887733, 2022). "Metabolic syndrome (MetS) is an independent risk factor for chronic kidney disease (CKD) through many mechanisms, including activation of the renin–angiotensin system." (PMID 36035416, 2022). "Although renin-angiotensin system blockers, as first-line therapy, can reduce proteinuria, they cannot prevent the progression to end-stage renal disease." (PMID 42216070, 2026). "In a couple of large, phase-3, placebo-controlled trials (FIDELIO-DKD and FIGARO-DKD), finerenone reduced both the progression of chronic kidney disease (CKD) and cardiovascular events in patients with CKD associated with type 2 diabetes (T2D) already on blockers of the renin–angiotensin system." (PMID 40299361, 2025). "Activities of the circulating and intrarenal renin‐angiotensin(‐aldosterone) systems (RA[A]S) are incompletely understood in people and cats with chronic kidney disease (CKD)." (PMID 40560995, 2025). "Chronic kidney disease (CKD) can predispose to HFpEF through arterial stiffening, volume expansion, renin-angiotensin-aldosterone system (RAAS) activation, and hypertension, all of which increase afterload." (PMID 39301908, 2025). "Chronic kidney disease leads to activation of the renin–angiotensin–aldosterone system, and this activation results in sodium and water retention, thereby increasing cardiac afterload." (PMID 41464691, 2025). "This article highlights the favorable renal outcomes achieved through optimized renin-angiotensin-aldosterone system (RAAS) blockade in an adult patient with chronic kidney disease (CKD) and significant proteinuria." (PMID 41189867, 2025). "Mesangial cells in tumors highly express genes such as CD36 (linked to chronic kidney disease), NDUFA4L2, and renin (REN), indicating a reactive nature to the TME." (PMID 41035074, 2025). "Vicadrostat, a selective aldosterone synthase inhibitor, reduced albuminuria with concurrent renin–angiotensin system inhibition and empagliflozin, suggesting additive efficacy for chronic kidney disease (CKD) treatment." (PMID 41303298, 2025). "This patient showed signs of arteriole remodeling and was found to have Stage III chronic kidney disease from the months to possible years of undiagnosed renin-mediated hypertension." (PMID 40546339, 2025). "The 2021 Guidelines for Managing Blood Pressure in Chronic Kidney Disease Patients with IgAN recommend using renin–angiotensin–aldosterone system blockers as conservative supportive therapy for IgAN to manage blood pressure and reduce proteinuria." (PMID 39221249, 2024). "This historical focus has paved the way for current therapeutic interventions, such as the use of renin-angiotensin system blockers which have become cornerstone treatments for chronic kidney disease." (PMID 38482598, 2024). "In this secondary analysis of the STOP-ACEi trial, we explored the impact of discontinuing or continuing renin–angiotensin system inhibitor therapy in people with advanced chronic kidney disease on cystatin C estimated glomerular filtration rate (eGFR)." (PMID 40034484, 2024). "Further investigations revealed a right acute hemorrhagic stroke, bilateral grade 4 hypertensive retinopathy, chronic kidney disease with end-stage renal disease, hypokalemia, and an elevated aldosterone/renin ratio." (PMID 38465123, 2024). "These SCFAs, stemming from the metabolite processes within the gut microbiota, have the power to influence kidney blood flow by activating the renin-angiotensin-system (RAAS), a system intricately associated with chronic kidney disease." (PMID 39090986, 2024).
chronic kidney disease (continued). "In chronic kidney disease, men progress faster to end-stage renal disease partly due to male hormones increasing oxidative stress, activating the renin–angiotensin system and exacerbating fibrosis in the injured kidney." (PMID 38534370, 2024). "Renin–angiotensin system (RAS) inhibitors are known to reduce proteinuria in patients with chronic kidney disease (CKD) by dilating the glomerular export arteries and reducing intraglomerular pressure." (PMID 38193991, 2024). "Currently, effective medical treatments for the retardation of chronic kidney disease (CKD) progression include the use of renin–angiotensin–aldosterone system blockers and sodium–glucose cotransporter 2 inhibitors." (PMID 39451219, 2024). "Here, it is essential to observe that, more often than not, patients who are on the KT waiting list with acute kidney injury (AKI), chronic kidney disease (CKD), and end-stage renal disease (ESRD) present with high-renin biotypes)." (PMID 39200281, 2024). "The Renin–Angiotensin System Inhibition in Advanced Chronic Kidney Disease (STOP-ACEi) trial provides further evidence tosupport the use of RAASi in patients with impaired renal function." (PMID 39076544, 2024). "Strict control of blood sugar and blood pressure, including the use of renin–angiotensin–aldosterone system inhibitors, can delay the progression of diabetic nephropathy but cannot prevent it from eventually developing into end-stage renal disease." (PMID 38779567, 2024). "The complicated operation of the renal renin-angiotensin system (RAS) is directly related to the onset of chronic kidney disease (CKD)." (PMID 37841924, 2023). "Autosomal dominant tubulointerstitial kidney disease (ADTKD), a rare genetic disorder characterised by progressive chronic kidney disease, is caused by mutations in different genes, including REN, encoding renin." (PMID 37283036, 2023). "In patients with chronic kidney disease, renal function and excretion are impaired, blood volume is increased, renin–angiotensin–aldosterone system is activated in a feedback manner, and water and sodium retention is aggravated." (PMID 37077571, 2023). "New treatment modalities are becoming available to prevent and delay the progression of chronic kidney disease in addition to standard treatment, which mostly include blockers of the renin-angiotensin-aldosterone system." (PMID 37344787, 2023). "As of now, the recommended first line of treatment to control the blood pressure in chronic kidney disease is the administration of renin–angiotensin–aldosterone system modulators." (PMID 36860293, 2023). "It is most often due to impaired renal potassium excretion due to acute on chronic kidney disease or the use of drugs that inhibit the renin-angiotensin-aldosterone axis." (PMID 37065408, 2023). "Caffeine consumption, on the other hand, has been shown to have a renal protective effect against chronic kidney diseases by increasing glomerular filtration rate and maintaining the renin-angiotensin system." (PMID 37306714, 2023). "Another example is topic 11 (plasma renin activity), topic 7 chronic kidney disease), and topic 18 (heart surgery) was often discussed in the same articles." (PMID 35583933, 2022). "There has been controversy about renin-angiotensin system (RAS) inhibition in IgAN patients with advanced (stage 4) chronic kidney disease (CKD)." (PMID 36660420, 2022). "So far, the main treatment delaying CKD progression and reducing the risk of end-stage renal disease is RAAS antagonists, including ACEI and ARB medications, as well as direct renin inhibitors." (PMID 35247964, 2022). "Patients in the two studies had a high intrinsic risk of hyperkalemia due to type 2 diabetes, treatment with optimized doses of an inhibitor of the renin‐angiotensin system, and, in some patients, their advanced chronic kidney disease." (PMID 36574588, 2022).
chronic kidney disease (continued). "Inhibition of the renin-angiotensin-aldosterone system (RAAS) is broadly recommended in many nephrological guidelines to prevent chronic kidney disease (CKD) progression." (PMID 36294504, 2022). "A total of 1177 patients (15.6%) had cardiovascular disease, and 1322 patients (17.5%) had chronic kidney disease; 3816 patients (50.6%) were receiving statin medications, and 3292 patients (43.7%) were receiving renin-angiotensin system inhibitors." (PMID 33929522, 2021). "The sympathetic overactivity typically displayed by patients with chronic kidney disease is favorably affected by drugs acting on the renin–angiotensin system." (PMID 33606138, 2021). "PGI2 is well known for its regulation of renal hemodynamics, tubular transport, and renin release and plays an important role by coupling with its receptors and the downstream signals in various types of renal diseases including chronic kidney disease." (PMID 33622285, 2021). "Ninety-eight patients (28.3%) had chronic kidney disease and almost half of the patients (49.4%) were chronically under renin–angiotensin–aldosterone system (RAAS) inhibitors." (PMID 34300311, 2021). "Renin–angiotensin–aldosterone system inhibitors can commonly increase serum potassium levels, which can limit their implementation in patients with chronic kidney disease." (PMID 34884224, 2021). "In patients with chronic kidney disease, MCs in the kidney were found to express chymase, tryptase, renin, and TGF-β1." (PMID 32098318, 2020). "Moreover, circulating HER2 has been identified as a causal mediator of chronic kidney disease (CKD) and can be regulated by the renin-angiotensin system." (PMID 32160892, 2020). "Early screening tests, including for levels of plasma aldosterone and renin, should be performed, as delay in diagnosis can lead to negative outcomes which include congestive heart failure, myocardial infarction and chronic kidney disease." (PMID 33228612, 2020). "The first phase of the published OPAL-HK study was a single-group treatment phase, which showed that patiromer normalised serum potassium at 4weeks in patients with chronic kidney disease stages 3–4 who were receiving renin-angiotensin-aldosterone inhibitors." (PMID 32853209, 2020). "Abundant evidence reveals that activation of the renin-angiotensin system promotes skeletal muscle atrophy in several conditions including congestive heart failure, chronic kidney disease, and prolonged mechanical ventilation." (PMID 32674346, 2020). "Angiotensin II (Ang II), a key molecule of the renin–angiotensin system (RAS), is a significant risk factor for the initiation and progression of chronic kidney disease (CKD)." (PMID 32770719, 2020). "CKD-specific non-classical risk factors include inflammation, anemia, volume overload, oxidative stress, renin–angiotensin system, sympathetic nerve system, uremic toxins, and chronic kidney disease-mineral bone disorder (CKD-MBD)." (PMID 30830548, 2019). "Carvedilol was found beneficial for patients with chronic kidney disease due to its ability to reduce cardiac output and renin release, as to its ability to reduce renovascular constriction through its alfa-1 and beta-1 receptor antagonism." (PMID 31391573, 2019). "Chronic kidney disease (CKD) can cause fluid retention, mainly due to reduced glomerular filtration of sodium and activation of the renin-angiotensin system." (PMID 31217504, 2019). "As a consequence of impaired renal function, patients with chronic kidney disease (CKD) are at increased risk of hyperkalaemia; and renin-angiotensin-aldosterone system inhibitor (RAASi) agents routinely indicated for CKD management are known to exacerbate this risk." (PMID 30134846, 2018). "Renin–angiotensin–aldosterone system (RAAS) inhibition is a major therapeutic approach for slowing chronic kidney disease (CKD) progression." (PMID 28805480, 2017).
chronic kidney disease (continued). "Therefore, additional recruitment of renin-producing cells and subsequent increase of intrarenal renin expression appear to be associated with chronic kidney disease (CKD)." (PMID 28753620, 2017). "Renin-angiotensin-system (RAS) blockade is thought to slow renal progression in patients with chronic kidney disease (CKD)." (PMID 28122064, 2017). "Rational: The inhibition of renin–angiotensin–aldosterone system (RAAS) is a major strategy for slowing the progression of chronic kidney disease (CKD)." (PMID 28805480, 2017). "The lack of correlation between kidney function impairment and aldosterone level as well as plasma renin activity is probably connected with wide use of nephroprotection, starting at the early stage of chronic kidney disease." (PMID 26885251, 2016). "The renin-angiotensin-aldosterone system (RAAS) is overactivated in patients with chronic kidney disease." (PMID 27732567, 2016). "The renin-angiotensin system (RAS) has been implicated in atherosclerotic lesions and progression to chronic kidney diseases." (PMID 26245758, 2015). "On the other hand, in patients with chronic kidney disease, renin-angiotensin system blockers are the drugs of first choice for achieving the goal of renal protection." (PMID 24672712, 2014). "Activation of the renin-angiotensin-aldosterone system (RAAS) is a typical finding in chronic kidney disease." (PMID 24797667, 2014). "The renin-angiotensin-aldosterone system (RAAS) is important in the development of chronic kidney disease (CKD)." (PMID 24255685, 2013). "The search terms used were “angiotensin-converting enzyme inhibitor”, “angiotensin receptor blocker”, “cardiovascular disease”, “chronic kidney disease”, “diabetes”, “direct renin inhibitor”, “dual RAS blockade”, “heart failure”, “myocardial infarction”." (PMID 23866091, 2013). "The pathogenesis of chronic kidney disease is multifactorial, and the renin-angiotensin aldosterone system (RAAS) is known to play an important role." (PMID 22917002, 2012). "Studies have shown that the decline in glomerular filtration or the development of end stage renal disease was delayed with the use of drugs acting on the of renin-angiotensin system (RAS) like ACEI or ARB." (PMID 23259489, 2012). "Inhibition of the renin-angiotensin-aldosterone system (RAAS) slows down the progression of chronic renal diseases (CKD) including IgA nephropathy (IgAN)." (PMID 21974877, 2011). "Reduction of proteinuria and blood pressure (BP) with blockers of the renin-angiotensin system (RAS) impairs the progression of chronic kidney disease (CKD)." (PMID 22073219, 2011). "Increased activation of the renin-angiotensin system (RAS) has been postulated to play a central role in the progression of chronic kidney disease (CKD) and coronary heart disease (CHD)." (PMID 19327134, 2009). "On the other hand, HF patients are more prone to develop OP and pathological fractures because of low vitamin D level, high PTH, chronic renal failure, alteration of renin–angiotensin–aldosterone system, reduced testosterone level, and metabolic effects derived from commonly used medications." (PMID 39997503, 2025). "Excessive activation of the renin‐angiotensin‐aldosterone system (RAAS) plays a critical role in the progression of chronic kidney disease (CKD) by triggering hemodynamic maladaptation and enhancing inflammation, fibrosis, and oxidative stress within the kidneys." (PMID 40560995, 2025). "Though the mechanisms of PlGF elevation in the context of chronic kidney disease are unclear, one hypothesis implies an upregulation of PlGF through toxin accumulation or renin-angiotensin-aldosterone stimulation." (PMID 40225361, 2025). "Previous population-based studies have reported an increased risk of cardiovascular disease, and a higher prevalence of chronic kidney disease and metabolic dysfunction-associated steatotic liver disease in patients with RIA compared with those with renin-dependent aldosteronism." (PMID 41473246, 2025).
chronic kidney disease (continued). "Early renin-angiotensin system blockade is the standard of care therapy; sodium-glucose cotransporter-2 inhibitors may be added in adults with proteinuria and chronic kidney disease." (PMID 39673454, 2025). "Accumulating evidence have shown that compared with individuals with renin-dependent aldosteronism, those with RIA face a heightened risk of cardiovascular disease, and a higher prevalence of chronic kidney disease and metabolic dysfunction-associated steatotic liver disease." (PMID 41473246, 2025). "UA may also cause endothelial dysfunction, activation of the renin–angiotensin–aldosterone system (RAAS), inflammation, and oxidative stress, leading to chronic kidney disease (CKD) and its progression." (PMID 40607026, 2025). "Hyperkalemia, a condition caused in part by chronic kidney disease (CKD), heart failure (HF), and renin–angiotensin–aldosterone system inhibitors (RAASi), is a serious electrolyte abnormality that can cause life-threatening arrhythmias, cardiac arrest, and sudden death." (PMID 39976633, 2025). "It is controversial whether renin-angiotensin system inhibitors (RASIs) should be stopped in patients with advanced chronic kidney disease (CKD)." (PMID 38438724, 2024). "Immunosuppressive agents and inhibitors of the renin-angiotensin system are the main treatments, but patients who are refractory to that may progress to chronic kidney disease stage 5 treated by dialysis (CKD G5D) or kidney transplantation." (PMID 39015674, 2024). "His biochemistry showed persistently elevated ARR with an aldosterone concentration ≥ 500 pmol/L (≥18 ng/dL) and suppressed direct renin concentrations ≤2 mU/L, with stage 3 chronic kidney disease and an estimated glomerular filtration rate (eGFR) of 50 mL/min/m2." (PMID 38887633, 2024). "Renin-angiotensin inhibitors are started to control urinary protein in protein-creatinine ratio > 0.2, and also maintenance measures are taken to prevent and treat the complications of chronic renal failure and eye and ear involvement." (PMID 37059980, 2023). "The renal renin-angiotensin system (RAS) is involved in the development of chronic kidney disease." (PMID 36520238, 2023). "This possibility is supported by the fact that diabetic complications could activate the renin-angiotensin system by accelerating atherosclerosis and chronic kidney disease." (PMID 35482752, 2022). "While melatonin has been shown to ameliorate chronic kidney disease via antioxidant effects and modulation of the renin-angiotensin system, the detailed interactions between the circadian clock and glomerular diseases are not elucidated and will be a highly interesting field for follow-up studies." (PMID 32302353, 2020). "Although urinary angiotensinogen (AGT) and renin reflect intrarenal renin-angiotensin system activity and are enhanced in proteinuric chronic kidney disease, the clinical value of urinary AGT and renin levels during antiproteinuric treatment has yet to be determined." (PMID 32410703, 2020). "While the inhibition of the renin-angiotensin-aldosterone system may provide some benefits for patients with DN, many continue to develop end-stage renal disease." (PMID 33343355, 2020). "Albuminuria or proteinuria was tested in approximately one-eighth of adults with chronic kidney disease, renin-angiotensin system inhibitors were prescribed to one-fifth, and nonsteroidal anti-inflammatory agents or proton pump inhibitors were prescribed to more than one-third." (PMID 31860111, 2019). "Renin-angiotensin-aldosterone system blockers (e.g., angiotensin-converting enzyme inhibitors, angiotensin II receptor antagonists) are usually prescribed in high risk AKI individuals, such as cardiovascular, chronic kidney disease, and elderly patients." (PMID 30646533, 2019). "We studied whether endothelin receptor antagonist and calcimimetic treatments influence renal damage and kidney renin-angiotensin (RA) components in adenine-induced chronic renal insufficiency (CRI)." (PMID 29078759, 2017).